TYR (tyrosinase)
Diseases named in the same sentence as TYR in open-access papers (continued):
Sharing a sentence is not in itself a finding about the gene and the disease.
melanoma (continued). "A recent study showed induction of immunity against metastatic melanoma through vaccination with mature DCs loaded with melanoma antigens (MART-1, MAGE-3, gp100 and tyrosinase) processed through melanoma constitutive proteasomes for presentation by MHC class I to cognate T cells." (PMID 24969320, 2014). "The first detection of melanoma CTCs was based on RT-PCR of tyrosinase." (PMID 24743024, 2014). "CGA is a likely a substrate of melanin, but the metabolic product(s) of CGA may suppress melanogenesis in B16 melanoma cells by inhibiting tyrosinase activity." (PMID 25157464, 2014). "In malignant melanomas this progeny is characterized by either the melanoma antigens HMB45 and MART-1, the microphthalmia-associated transcription factor (MITF) or the melanin synthesis controlling enzyme tyrosinase (TYR)." (PMID 24799129, 2014). "The results of cell experiments showed EAE could strongly inhibit cellular tyrosinase activity, which had led to the decrease of melanogenesis in B16 mouse melanoma cells." (PMID 25045392, 2014). "Similarly, mammalian tyrosinase has been purified from various sources such as pigmenting melanoma cells." (PMID 24392141, 2014). "Indeed, while tyrosinase is overexpressed in melanoma and is a target of melanoma immunotherapy, LEC-mediated self-tolerance to tyrosinase limits active immunotherapy." (PMID 25580369, 2014). "The selection of melanoma cell lines reflects the heterogeneity of the original tumors and includes highly differentiated cell lines (D10, WM115, HBL) expressing the melanoma differentiation antigens gp100, tyrosinase, and MART-1, and undifferentiated cell lines." (PMID 23915418, 2013). "It was demonstrated that the phenol NPrCAP, as a prohapten, can be activated in melanoma cells by tyrosinase to the reactive quinone-hapten NPrCAQ which binds to melanosomal proteins through their cysteine residues to form possible neo-antigens, thus triggering the immunological response." (PMID 23533767, 2013). "Furthermore, multiple melanoma antigens, including tyrosinase, TRP1, TRP2, and gp100, contain disulfide bonds and likely contain GILT-dependent epitopes." (PMID 24409178, 2013). "According to this hypothesis, tyrosinase could be recognized as a melanoma-specific tumor antigen in relation to the systemic immune responses." (PMID 23533767, 2013). "These EVs were enriched with vesicular marker proteins (CD9, CD81 and Tsg101), tyrosinase, F4/80, alpha-smooth muscle actin and E-selectin, suggesting that melanoma cell-, macrophage-, fibroblast- and endothelial cell-derived EVs are present in the melanoma microenvironment." (PMID 26082317, 2013). "Thus, tyrosine analogues that are tyrosinase substrates can be good candidates for developing drugs to melanoma-targeting therapies." (PMID 23533767, 2013). "It was also hypothesized that the degradation of melanoma tissues may occur from oxidative and heat stresses by exposure of NPrCAP to tyrosinase and by exposure of magnetite nanoparticles to AMF." (PMID 23533767, 2013). "VID is able to increase TYR activity in B16 melanoma cells and promote melanin synthesis; however, it is still controversial whether VID is able to promote melanin synthesis in normal epidermal melanocytes." (PMID 24137299, 2013). "To identify the active compound arctigenin in Fructus Arctii (dried seed of medicinal plant Arctium lappa) and to elucidate the inhibitory mechanism in melanogenesis, we analyzed melanin content and tyrosinase activity on B16BL6 murine melanoma and melan-A cell cultures." (PMID 23781272, 2013). "Many pigmentation genes linked to melanoma in recent GWAS such as TPCN2, ASIP, KIT, NCKX5, TYR, IRF 4, OCA2 and TYRP1 have been linked to melanoma and some of them like MC1R have dual roles in pigmentation and immune responses but many other functions of these genes remain to be discovered." (PMID 23796690, 2013).
melanoma (continued). "Control cultures, assessed at day 5 of the culture time (at the moment of the heat treatment), was in a pre-confluent stage, as referred above, and expressed several typical melanoma genes, namely TYR, TRP-1, TRP-2 and pMel17, genes that are involved in melanin synthesis." (PMID 22532856, 2012). "Large numbers of melanoma-associated antigens (MAA) have been identified as well as the development of spontaneous T cell reactions and antibody production against various antigens (such as Melan-A, gp100, tyrosinase or NY-ESO-1) has been reported in patients with advanced melanoma." (PMID 24213320, 2012). "Importantly, primary skin tumors developed in ret transgenic mice were found to express several differentiation MAA such as TRP-1, TRP-2, gp100 and tyrosinase, which have been previously identified as targets for tumor-reactive T cells in melanoma patients." (PMID 24213320, 2012). "Whether EDEM1 may play an active role in the enhanced antigen presentation of tyrosinase peptides in melanoma cells is currently under investigation." (PMID 22905195, 2012). "Inherited mutations cause a genetic predisposition to melanoma, including mutations in cell cycle genes such as CDKN2A, CDK4, RB1 and MDM2, as well as melanocyte differentiation and activation genes such as MC1R, TYR, TYRP1 and ASIP." (PMID 22536322, 2012). "It is the objective in this study to investigate if this oxidative stress might interfere with tyrosinase activity and melanogenesis in murine B16 melanoma cells." (PMID 22412813, 2012). "The interaction between α-Syn and TYR could be the explanation for the reduction of UVB light-induced increase of melanin synthesis and TYR activity in α-Syn-expressed melanoma cells." (PMID 23028833, 2012). "The immunogenic role of tyrosinase in melanoma has been already proved, and results presented in this work are in accordance with previously published papers on the presence of anti-tyrosinase antibodies in the serum of control people as well as in patients with melanoma or vitiligo." (PMID 22834951, 2012). "Our results also revealed that UVB light exposure caused an increase of TYR activity by 112% in α-Syn-suppressed SK-MEL-28 melanoma cells as compared to its non-UVB light-exposed control cells." (PMID 23028833, 2012). "3,4-dihydroxyphenylalanine (L-dopa) is the first metabolite involved in melanogenesis and its plasma levels have been correlated with melanoma progression and tumor burden, as well as the plasma L-dopa/L-Tyrosine ratio which represents an index of tyrosinase and tyrosine hydroxylase activity." (PMID 22287956, 2012). "Tyrosinase is rate-limiting enzyme for melanin production, which is highly expressed in melanomas." (PMID 21453283, 2011). "It is a DNA vaccine expressing human tyrosinase (therefore defined as xenogeneic vaccine) against canine malignant melanoma, and delivered via a Transdermal Device, developed in conjunction with Bioject Inc, which delivers the vaccine without the use of a needle." (PMID 24212974, 2011). "Freshly isolated human melanoma cells, obtained from metastatic melanoma patients, were isolated and cultivated for a few passages or used directly (primary melanoma T14, T15) for binding of antimelanoma antibodies (Melanin A, Tyrosinase, HMB45)." (PMID 21179030, 2011). "Treatment with monobenzone, a compound which results in melanocyte killing through haptenization of tyrosinase and induction of melanocyte autophagy, also leads to rejection of B16 melanoma tumors and the development of vitiligo when combined with TLR agonists." (PMID 21911918, 2011). "The inhibition effect of melanoma cell growth with the use of MIA promoters with four tyrosinase gene enhancers is only slightly lower to the effect of the construct with the CMV-promoter; however, the latter does not provide the selectivity of transgene expression." (PMID 22649681, 2011).
melanoma (continued). "Due to the high stringency of our search, ESTs for genes traditionally known as melanocyte/melanoma-specific genes, such as TYR (Hs.503555), DCT (Hs.301865), MLANA (Hs.154069), and SILV (Hs.95972), were not selected because they also match entries of other tissue datasets." (PMID 20975957, 2010). "A slightly different version of tyrosinase promoter/enhancer combination has been claimed to reach, at least in a very limited number of melanoma cells, comparable expression levels as from CMV promoter, whereas others found only maximal 1.3% of the CMV promoter-driven transcriptional activity." (PMID 20670430, 2010). "This is comparable with earlier reports, where a recombinant Ad expressing β-Gal under the control of two copies of the mouse tyrosinase enhancer in combination with a 770 bp mouse tyrosinase promoter gave rise to 100- to 200-fold higher expression in melanoma cells compared to non-melanoma cells." (PMID 20670430, 2010). "Of interest, inhibition of Hsp90 resulted in induction of differentiation in the melanoma lines used, as shown by the characteristic increase in the dendritic cell morphology and expression of the melanocyte lineage marker tyrosinase in both CHL-1 and SKMEL28 cells." (PMID 21037799, 2010). "In this study, 8-OHDe was evaluated for in vitro cellular tyrosinase and melanogenesis inhibitory activities in mouse B16 melanoma cells and for in vivo skin-whitening activity in human volunteers, and the depigmenting activities of the compound in both assay systems were confirmed." (PMID 20057943, 2009). "Mulberroside F (moracin M-6,3′-di-O-β-glucopyranoside) purified from the leaves of the plant showed the antidiphenolase activity of mushroom tyrosinase to be 4.5-fold higher than that of kojic acid and exhibited an inhibitory effect on melanin formation within melanoma cells." (PMID 19582213, 2009). "Therefore, the depigmenting effect of catechins is due to direct inhibition of tyrosinase activity and down-regulation of tyrosinase expression of B16 melanoma cells." (PMID 19924076, 2009). "In albino melanocytes or in amelanotic melanoma cells, the aberrant retention of tyrosinase in the ER and its subsequent degradation occur owing to the quality-control machinery, indicating that oculocutaneous albinism, at least in part, is an ER retention disease." (PMID 20057953, 2009). "Tyrosinase is a type 1 transmembrane protein that is often found in melanoma." (PMID 20016802, 2009). "In the present work we expressed the HPV 16 E5 protein in two lines of human, tyrosinase-positive, amelanotic melanomas with the aim to examine whether the E5 expression could modulate the melanosomal pH and tyrosinase activity." (PMID 19133143, 2009). "Importantly, the peptide/MHC tetramers used in this study can only detect a miniscule fraction of the possible CD8+ T cells that have specificity for MART1, gp100, tyrosinase or other melanoma antigens." (PMID 18334033, 2008). "Moreover, Mo-MLV based retroviral vectors with hybrid LTRs incorporating large portions of the melanoma-specific murine tyrosinase enhancer/promoter also had titers in the range of 103cfu/ml." (PMID 16603064, 2006). "Furthermore, in total RNA and in vitro transcribed RNA we monitored the presence of melanoma-specific transcripts gp100, tyrosinase, and MART1 by RT-PCR." (PMID 16911798, 2006). "In favour of this hypothesis, it has been shown that these reactive forms could be produced by tyrosinases in melanoma cells and that toxicity of etoposide depended on presence of tyrosinase." (PMID 15999103, 2005). "However, the prognostic role of tyrosinase expression in the peripheral blood of melanoma patients after the excision of primary lesion and/or nodal dissection has not yet been fully clarified." (PMID 14562017, 2003).
melanoma (continued). "Even if tyrosinase expression in the peripheral blood of melanoma patients has been widely reported in the literature, only a few papers have been specifically addressed to the evaluation of tyrosinase expression both at diagnosis and during the follow-up of stage III disease-free patients." (PMID 14562017, 2003). "Therefore, TYR inhibitors can also be serve as an adjuvant therapy for melanoma." (PMID 40005101, 2025). "Furthermore, research into the role of tyrosinase in the immune response to melanoma may lead to the development of more effective immunotherapy strategies." (PMID 40332760, 2025). "Previous studies have indicated that chrysin may exert anti-photoaging and anti-melanogenesis effects in human dermal fibroblasts and B16 murine melanoma cells by blocking TYR activity and attenuating the expression of melanogenic proteins, involving TYR, TRP-1, and TRP-2." (PMID 39882455, 2025). "B16F0 murine melanoma cells were selected for melanin quantification due to their high pigment production and common use in melanogenesis studies, whereas A375 human melanoma cells were used for tyrosinase expression analysis to validate THC’s effects in human melanoma at the protein level." (PMID 41446503, 2025). "Additionally, molecular docking of these compounds to the enzyme’s active site was conducted, and their ability to inhibit melanogenesis and cell proliferation in melanoma cell lines with high tyrosinase (TYR) expression—SK-MEL-3—and its low-expression counterpart, Hs294T, was investigated." (PMID 41155937, 2025). "Our UV–Vis spectroscopic results indicate also that carbazole–thiazoles exhibit high tyrosinase inhibitory activity, comparable to the activity of kojic acid and are several-times more active than ascorbic acid, which suggests that they can be used in melanoma therapy and food processing." (PMID 39409408, 2024). "Tyrosinase (TYR), a copper-containing polyphenol oxidase that regulates melanin synthesis, has been identified as a candidate biomarker for melanoma due to its overexpression in melanoma cells and accumulation in skin cells, which correlates with the severity of malignancy." (PMID 38667195, 2024). "However, CD271(+) melanoma cells lack expression of typical melanoma cell surface markers such as TYR, MART, and MAGE, leading to the speculation that CD271+ melanoma cells may be in a state of incomplete differentiation." (PMID 39611156, 2024). "Additionally, Hom Thong banana peels are rich in phenolic compounds that could inhibit melanin content and tyrosinase activity in both human and mouse melanoma cells." (PMID 39684912, 2024). "Furthermore, the tyrosinase-dependent cytotoxicity in B16BL6 melanoma cells was also examined." (PMID 39337478, 2024). "In addition, quercetin is metabolized by tyrosinase, which is expressed in melanocytes, and tyrosinases converted into anticancer compounds may show increased potency against specific melanomas." (PMID 39161800, 2024). "Additionally, the aqueous, 50%, and 95% ethanolic extracts of B. alba demonstrated significant inhibitory effects on cellular tyrosinase activity in the IBMX-induced melanoma cells, with values of 94.07 ± 1.05%, 89.63 ± 5.24%, and 99.26 ± 4.19% of the control, respectively (p < 0.05)." (PMID 39335872, 2024). "In this study, 6M-4MC was shown to activate melanin production in B16F10 melanoma cells by upregulating tyrosinase, TRP-1, and TRP-2, indicating that 6M-4MC may stimulate intracellular tyrosinase activity by enhancing the expression of these melanogenesis-related enzymes." (PMID 39596485, 2024). "Notably, we also observed reduced expression of genes involved in growth, increased expression of genes involved in tumor suppression, and promotion of an anti-tumor immune environment when Cxcr2 was deleted in tyrosinase-expressing melanoma precursor cells during transformation." (PMID 37270599, 2023).
melanoma (continued). "Also, we found that A-alum-1 was able to modestly suppress the α-MSH-induced mRNA expression of MITF and tyrosinase in human melanoma SK-mel-28 cells, similarly to that in B16F1 cells, suggesting that A-alum-1 can inhibit melanogenesis through a transcriptional suppression-mediated mechanism." (PMID 37834109, 2023). "Taken together the research suggests that ferulic acid may regulate tyrosinase activity, inducing pathways of melanogenic or whitening effects dependent on concentration, that has further mechanistic implications for the regulation of melanoma tumorigenesis." (PMID 36614303, 2023). "Notwithstanding all these promising coumarin derivatives found in the literature, herein, we performed an investigation focused on an in-house library of coumarins, aiming to identify potential inhibitors of the tyrosinase enzyme, which could be promising drug candidates against melanoma." (PMID 36982292, 2023). "In addition, small interfering RNA-mediated MITF silencing in melanoma cells significantly reduces melanin content by inhibiting TYR, TYRP-1, and MC1R, which indicates that the transcriptional activation of MITF is a promising strategy for treating hypopigmentation." (PMID 36235048, 2022). "Furthermore, the authors report apigenin-7-glucoside and naringenin as possessing the ability to enhance the melanogenesis synthesis and tyrosinase activity of B16F10 melanoma cells, whereas genkwanin, by inhibiting tyrosinase activity, can induce a decrease in melanin synthesis." (PMID 35458783, 2022). "The resultant human tyrosinase protein is at least 85% homologous (with some reports up to 92% homologous) to canine tyrosinase, therefore both different enough to elicit an immune response, and similar enough to provide an appropriate target in the canine melanoma cells." (PMID 36356074, 2022). "Furthermore, the cytocompatibility and anti-tyrosinase activity were assayed in melanoma cells." (PMID 35890482, 2022). "Therefore, it could be considered as potential lead molecule for the design and development of selective tyrosinase inhibitors applicable to skin whitening and to malignant melanoma anticancer agents, and with lesser side effects." (PMID 36142889, 2022). "In B16F10 murine melanoma cells, 1a and 1b dose-dependently and significantly inhibited melanin production intracellularly, and melanin release into medium more strongly than kojic acid, and these effects were attributed to the inhibition of cellular tyrosinase." (PMID 35883866, 2022). "Whilst the occurrence of the whitening effect is inseparable from the production of melanin and the activity of tyrosinase, studies have found that pearl extracts and hydrolyzed pearl can reduce the activity of tyrosinase in B16 melanoma cells, thereby inhibiting melanin production." (PMID 36081944, 2022). "Furthermore, we show that inhibition of tyrosinase activity in pigmented melanoma cells affects melanoma-mononuclear cell crosstalk and induces significant amplification of proinflammatory cytokines expression in co-cultured human peripheral blood mononuclear cells (PBMCs)." (PMID 34072104, 2021). "Caff was able to inhibit MICs’ proliferation and spheroid formation in a dose-dependent manner, as well as their melanin production (a melanoma differentiation marker), confirming the in silico data and the hypothesis that one of the key players of Caff’s action on melanoma cells is TYR." (PMID 34199192, 2021). "In this study, we examined the effects of morin on the melanin contents and tyrosinase activity, as well as the protein expression levels of the melanogenic enzymes TRP-1, TRP-2, and microphtalmia-associated transcription factor (MITF) in B16F10 mouse melanoma cells." (PMID 33917985, 2021). "Therefore, controlling a tyrosinase-dependent mechanism of melanogenesis might be the basis for a potential anti-melanoma therapy." (PMID 33922836, 2021).